ZNF230 (zinc finger protein 230)
Description:
May be involved in transcriptional regulation.
Synonyms: FDZF2
Tractability: PROTAC: ubiquitination databases record sites on it.
Gene: Protein-coding gene on chromosome 19 (44,002,934 to 44,013,924, forward strand). Ensembl gene ENSG00000159882.
Subcellular location: Nucleus
Subcellular location (Human Protein Atlas): Mitochondria
Pathways (Reactome):
Gene expression (Transcription): Generic Transcription Pathway
Gene Ontology:
Molecular function: protein binding; DNA-binding transcription factor activity
Biological process: regulation of DNA-templated transcription
Cellular component: nucleus
Genetic constraint (gnomAD): Loss-of-function variants: 13 observed, 11.59 expected, observed/expected ratio (o/e) 1.12, 90% interval 0.73 to 1.73. The upper end of that interval is the gene's LOEUF score, 1.73, which puts it in group 6 of 6, group 1 being the genes least tolerant of losing a copy. Missense variants: 532 observed, 592.03 expected, observed/expected ratio (o/e) 0.9, 90% interval 0.84 to 0.96. Synonymous variants: 174 observed, 204.13 expected, observed/expected ratio (o/e) 0.85, 90% interval 0.75 to 0.97.
Homologues: Orthologues: chimpanzee ZNF230 (99% identical), macaque ZNF230 (96% identical), dog ZNF227 (59% identical). Paralogues in human: ZNF155 (80% identical), ZNF223 (80% identical), ZNF222 (79% identical), ZNF233 (47% identical), ZNF285 (42% identical), ZNF214 (41% identical), ZNF527 (38% identical), ZKSCAN7 (37% identical), ZNF287 (37% identical), ZNF34 (36% identical), ZNF416 (36% identical), ZNF852 (36% identical), and 38 more.
Diseases named in the same sentence as ZNF230 in open-access papers:
ZNF230 is named in the same sentence as 1 disease in open-access papers, as found by Europe PMC text mining. Sharing a sentence is not in itself a finding about the gene and the disease. The quoted sentences say what the papers report.
cancer (1 paper, 2024). A tumor composed of atypical neoplastic, often pleomorphic cells that invade other tissues. "Again, selective upregulation of transcriptional and epigenetic regulators in responders is evident; examples include PRDM5, ZNF230, ZCCHC9, ZKSCAN4, and the epigenetic regulator ALKBH3, which demethylates DNA and RNA in cancer cells." (PMID 39450169, 2024).